TREM2 (triggering receptor expressed on myeloid cells 2)
Diseases named in the same sentence as TREM2 in open-access papers (continued):
Sharing a sentence is not in itself a finding about the gene and the disease.
tumor (continued). "In the present study, we aimed to develop a single therapy for CRC using CAR-T cell delivery of a combined PD-1-TREM2 single-chain fragment variable (scFv) derived from anti-TREM2 and anti-PD-1 antibodies designed for specific localization at the tumor site." (PMID 37563723, 2023). "To understand the spatial localization of Trem2+ cells in relation to the different tumor epithelial states in mice, we co-stained Trem2 and Ly6d in mouse BCCs." (PMID 37164949, 2023). "In cancer immunology, accumulating evidence suggests a pathological role of Trem2 in establishing an Immune-suppressive tumor niche in malignancies." (PMID 36982629, 2023). "Overall, our analysis establishes SCAMs as a tumor-specific Trem2+ population within the Ly6d- LT proliferative neighborhood, suggesting a unique role within the TME." (PMID 37164949, 2023). "The absence of TREM2 enhances the anti-PD-1-mediated immunotherapy in CRC animal models, with a study revealing that MC38 tumor growth was significantly inhibited in Trem2–/– mice compared to that in wild-type mice." (PMID 37563723, 2023). "TREM2 promotes T cell dysfunction and immunosuppressive activity of myeloid cells in tumor microenvironment." (PMID 37335084, 2023). "TREM-2-deficiency enhances the efficacy of the anti-PD-1 treatment and antibody-dependent TREM-2 blockade is sufficient to remodel the intra-tumour myeloid compartment and to slow tumour growth." (PMID 36161514, 2023). "Since the tumor microenvironment often hinders immunotherapeutic efficacy, targeting TREM2, particularly in conjunction with anti-PD-1 therapy, has been found to suppress tumor growth." (PMID 38203185, 2023). "SPP1+ macrophages expressed MRC1 (M2 marker), and TREM2 which correlates with tumor infiltrating CD8 exhaustion." (PMID 37633924, 2023). "Nonetheless, SPP1, APOE, and TREM2 manifested more average fold changes than the C1Q genes and were expressed in more tumor cells than normal tissue cells." (PMID 37187751, 2023). "The TREM2 gene expression levels were selected that were positively correlated with tumor purity in various cancer types." (PMID 36741909, 2023). "The cell-specific TREM2 functions, such as in fibroblast and stromal cells are different than the actual tumor microenvironment." (PMID 37335084, 2023). "HES1+ TAMs and TREM2+ TAMs were preferentially located in the tumor tissue while IL-4I1+ TAMs were enriched at the tumor periphery." (PMID 36845555, 2023). "Triggering receptor expressed on myeloid cells 2 (TREM2) has been found on tumor cells, TAMs, and myeloid cells." (PMID 37822933, 2023). "There, TREM2 is perhaps a biomarker to alter tumor bone marrow infiltration and reinforce immunotherapy of ICIs." (PMID 36844870, 2023). "Cluster 3 expressed monocyte markers such as Plac8 and Ly6c2 while all other clusters highly expressed tumor associated macrophage (TAM) marker Mrc1 and Trem2." (PMID 37954069, 2023). "Among these genes, SPINT2, LNX1, FOXA2, and SOSTDC1 were reported to be related to tumor progression, whereas TYROBP, TREM2, IL23R, CSF2RB, TRAF1, and TGFBR1 were closely associated with immune response." (PMID 36611170, 2023). "High TREM2, PD-L1 and CD32a expressions at the tumour leading edge are predictors of poorer overall survival, independent of clinical factors." (PMID 37324244, 2023). "TREM-1 and TREM-2 are expressed on MDSCs and TAMs and correlate with tumour increased volume in preclinical 4T1-breast cancer model." (PMID 36161514, 2023). "We found HLA-DR, Iba1, CD68, TREM2, P2RY12, CD64, CD16 and CD32a immunolabelled tumour-associated microglia and perivascular macrophages in the tumour cores." (PMID 37324244, 2023). "In the context of GBM, one study indicated that TREM2 expression was correlated with poor tumor immunity and worse prognosis, and that knockdown of TREM2 resulted in a decrease in M2 polarization." (PMID 37791581, 2023).
tumor (continued). "TREM2 is overexpressed on TAMs in 75% of human tumors and its expression highly correlates with poor tumor prognosis in patients." (PMID 37771596, 2023). "Comparison of the gene expression of TREM2+ TAMs between the tumor and adjacent normal tissue revealed that TREM2, SPP1, APOE, C1QA, C1QB, and C1QC were upregulated in tumors, which was consistent with the results for GSE160269." (PMID 37187751, 2023). "The overexpression of TREM2 always promotes the invasion, proliferation, and migration of tumor cells." (PMID 36741909, 2023). "We found that the addition of anti-Trem2 antibodies led to a slowing of tumor growth as compared to anti-IgG controls, further supporting the role of Trem2+ cells in tumor growth." (PMID 37164949, 2023). "Immunohistochemistry analysis revealed enhanced TREM2 expression in a significant number of cells in the tumor tissues of patients with CRC compared to that in resected normal specimens." (PMID 37563723, 2023). "While these data overall support TREM2 contributing to tumor suppressing activity in HCC and CRC, mechanistic conclusions are clouded by the global deletion of TREM2." (PMID 36119485, 2022). "TREM2 was expressed in “malignancy-associated” macrophages, with the highest levels in the C1QC+ subset that specifically accumulated in the tumor compared to the healthy counterpart." (PMID 35746551, 2022). "NSCLC patients with high TREM2+ TAM infiltration had a lower objective response rate to ICT compared to patients with low numbers of TREM2+ TAMs and were more likely to experience tumor progression following PD-1 blockade." (PMID 36119485, 2022). "Using NSCLC tissue microarrays, it was noted that higher TREM2 expression positively correlated with advanced tumor stages, shortened overall survival, and recurrence-free survival." (PMID 35746551, 2022). "Immunostaining was performed to confirm the expression pattern of TREM2 and its correlation with M2 subtype macrophages, suggesting that TREM2 was intimately related to the tumor immune microenvironment." (PMID 36713360, 2022). "The Macro-2 population expressed high levels of TREM2 in the tumor fractions and expression of TREM2 has been shown to be elevated in malignant tumors, including RCC67." (PMID 36180422, 2022). "We assessed the hepatic monocyte–macrophage composition in the TCGA-LIHC cohort and found that the fraction of infiltrating TREM2+ LAM-like cells was significantly increased in tumor samples compared to normal tissues." (PMID 35359989, 2022). "The accumulation of TREM2-expressing TAMs was reported across numerous cancer patients and tumor models." (PMID 35746551, 2022). "Genetic or therapeutic inhibition of Trem2, a hallmark gene of the disease-associated microglia (DAM) phenotype, was recently shown to license ICB therapy in murine tumor models." (PMID 36309495, 2022). "Human peripheral blood mononuclear cells (PBMCs) and single-cell suspensions of tumor and healthy adjacent tissues were analyzed for the presence of TREM2+ macrophages and TAMs using flow cytometry." (PMID 36230558, 2022). "Remarkably, we observed that FOXP3+ Treg cells and TREM2+CD163+ macrophages colocalized within the tumor ecosystem by employing multicolor immunofluorescence staining." (PMID 35359989, 2022). "Among all the major cell types, we found that TREM2 was mainly expressed in myeloid cells, the proportion of which was significantly higher in tumor samples than in adjacent liver tissues." (PMID 35359989, 2022). "In this review, we discuss evidence that TREM2 contributes to tumor suppressing or oncogenic activity when expressed by epithelial tumor cells." (PMID 36119485, 2022). "Bioinformatics analysis initially showed that TREM2 was differentially expressed in the PTC tumor microenvironment." (PMID 36438899, 2022). "Tumor growth attenuation was observed in the Trem2-/- mice compared to the Trem2+/+ mice with both cell lines." (PMID 36119485, 2022).
tumor (continued). "Consistent with this, SPP1 and TREM2 expression were significantly increased in the tumor fraction compared to the adjacent normal kidney tissue." (PMID 36180422, 2022). "Recent work by Drake and colleagues uncovered a tumor-specific C1Q+TREM2+APOE+ macrophage population in clear cell renal carcinoma associated with post-surgical disease recurrence for patients." (PMID 36119485, 2022). "Our laboratory and Ido Amit’s laboratory independently described the role of TREM2 in tumor immunity using either TREM2 genetic ablation or pharmacological blockade." (PMID 35746551, 2022). "Conversely, TREM2-overexpressing MC38 CRC cells resulted in decreased tumor volume following subcutaneous injection in mice." (PMID 36119485, 2022). "In the current study, we systematically interrogated the single-cell transcriptomes of human HCC tissues and found that TREM2 was enriched in a macrophage subgroup derived from tumor tissues that resemble LAMs." (PMID 35359989, 2022). "In the anti-PD-1 resistant colon carcinoma model CT26, the combination of anti-TREM2 and anti-PD-1 elicited tumor rejection in 20–60% of treated mice, along with increased infiltration of activated CD8 T cells." (PMID 35746551, 2022). "The results confirmed the preferential enrichment of the TREM2+ LAM-like cells subpopulation in tumor samples, demonstrating the rationality of our cluster identification." (PMID 35359989, 2022). "Survival analysis further showed that HCC patients with TREM2+ macrophage enrichment in tumor tissues had significantly shorter survival." (PMID 35359989, 2022). "The strip chart showed that the high TREM2+ macrophage group was significantly more likely to have advanced tumor grade, pathologic stage, and T stage." (PMID 35359989, 2022). "Spatial analysis of TREM2 expression by IHC within tumors shows TREM2+ macrophages are primarily localized in the tumor nest in hepatocellular, lung, and pancreatic carcinomas." (PMID 36119485, 2022). "Consistently, TREM2 expression in the tumor was correlated with reduced survival in patients with CRC and TNBC." (PMID 35746551, 2022). "Integrative analysis of single-cell data and spatial transcriptomic profiling of these tumors further revealed a modulatory axis from SLS tumor cells to suppressive TREM2+/TYROBP+ macrophages, leading to T-cell dysfunction." (PMID 36028490, 2022). "In both studies, silencing of TREM2 resulted in decreased cell proliferation and increased apoptosis in vitro and decreased tumor volume in vivo with subcutaneous cell injection models." (PMID 36119485, 2022). "Macro-2 was separated from the other macrophage clusters by overexpressing TREM2 and SPP1, two genes that have been associated with tumor angiogenesis and immune checkpoint therapy." (PMID 36180422, 2022). "Administration of an anti-CD8 monoclonal antibody in both Trem2+/+ and Trem2-/- mice accelerated tumor growth compared to the controls." (PMID 36119485, 2022). "TREM2 inhibition of the tumor-infiltrating macrophages suppressed tumor growth and enhanced checkpoint blocking therapy in preclinical studies." (PMID 36180422, 2022). "Secondly, we examined TREM2 expression in OSCC tumor tissues, healthy adjacent tissues and peripheral blood mononuclear cells (PBMCs) to reveal its link to macrophages." (PMID 36230558, 2022). "TREM2 was recently described as a marker of immunosuppressive TAMs, being part of a gene signature that was partially consistent across different tumor types and models." (PMID 35746551, 2022). "A simultaneous single-cell analysis of immune cells from tumor lesions, normal lung tissue, and the blood of each patient identified a subset of TREM2-expressing macrophages specifically enriched in tumors." (PMID 35746551, 2022). "Here, we will provide an overview of the impact of TREM2 on myeloid cells and then focus on the most recent literature on TREM2 in tumor immunology." (PMID 35746551, 2022).
tumor (continued). "Histological analysis showed that FOLR2+ macrophages were primarily localized in the tumor stroma, while TREM2+ TAMs were found both in the stroma and in tumor nests, especially along the invasive margin and forming cell clusters." (PMID 35746551, 2022). "Summary of mouse studies with supporting evidence for TREM2 contributing to tumor suppressing or oncogenic activity in different types of cancer." (PMID 36119485, 2022). "An important first step to understanding the role of TREM2 in cancer was to determine which cell type expresses TREM2 in the tumor microenvironment (TME)." (PMID 36119485, 2022). "The IHC analysis indicated that higher in tumor tissues expressed higher CD163+TREM2+ compared with para-tumor did." (PMID 35017463, 2022). "Collectively, our data clearly showed that TREM2 promoted NK cell development and tumor regression, suggesting TREM2 as a new candidate for cancer immunotherapy." (PMID 33980160, 2021). "This indicates that using approaches targeting molecules of immunosuppressive myeloid cells such as CSF1R and TREM2 would partially affect the endogenous anti-tumor TAM component." (PMID 34220848, 2021). "For example, myeloid cell TREM2 reprogrammed tumor microenvironement and the anti-TREM2 treatment promoted responsiveness of anti-PD-1 immunotherapy." (PMID 34135914, 2021). "The metastasis of tumor cells in the lung tissue was reduced, and the survival rate of WT mice transplanted with BMs from TREM2-TG mice was higher than that of mice transplanted with BMs from WT mice." (PMID 33980160, 2021). "Taken together, we detected an increase in Cq-TAMs and an increase in the expression of Chil3, Trem2, C1qa, and C1qb in the tumor compared with the normal pancreas." (PMID 33782087, 2021). "The tumor volume in tumor-bearing WT mice transplanted with BMs from TREM2-TG mice was lower than that in WT mice transplanted with BMs from WT mice." (PMID 33980160, 2021). "The observation found that tumor macrophage infiltrates enhanced T-cell-mediated control of tumor growth after the anti-TREM2 therapy; the anti-TREM2 mAb to tumor-bearing mice blunted tumor growth and strongly enhanced the efficacy of anti-PD-1 immunotherapy." (PMID 35003090, 2021). "Inhibitors of CSF1R, CCL2 and CCR2, CD47/SIRPα complex antagonists, CD40 agonist antibodies, and inhibitors of PI3Kγ and TREM2 protein are undergoing clinical evaluation for various tumor types." (PMID 34638378, 2021). "Our study reveals that TREM2 can function as a prognostic marker in various malignant tumors because of its role in tumorigenesis and tumor immunity." (PMID 33679809, 2021). "The resulting heatmap indicated that almost all immune-related genes were co-expressed with TREM2 and the majority were positively correlated with TREM2 in all types of tumor, except DLBC and LAML (p < 0.05)." (PMID 33679809, 2021). "Here, we demonstrated that overexpression of TREM2 promoted NK cell differentiation and enhanced their cytotoxicity toward tumor cells in vivo and in vitro." (PMID 33980160, 2021). "We then analyzed single-cell RNA sequencing data from patient tumors and novel single-cell RNA sequencing data from liver metastases and identified macrophages expressing high levels of C1QA, C1QB, and TREM2 in both primary tumor and metastases." (PMID 33782087, 2021). "The protein activity of the C1Q family of proteins, APOE, and TREM-2 was significantly upregulated in macrophages in tumors compared to non-tumor tissues." (PMID 34831009, 2021). "Our results show that TREM2 can be used as a prognostic factor for a variety of cancers, and TREM2 can play an important role in tumor immunity by affecting tumor infiltrating immune cells, TMB, and MSI." (PMID 33679809, 2021). "Macrophages can fuse with tumour cells and contribute to tumour heterogeneity, but a potential role of Trem2 in this process is yet to be found." (PMID 34794433, 2021).
tumor (continued). "In this study, we first review the structure of TREM2 and the pathway of TREM2 signaling, then we focus on the role and potential of the tumor suppressor TREM2 in the regulation of tumor immune system and cancer immunotherapy." (PMID 34539652, 2021). "With the rapid emergence of different studies, TREM2 has been reported to affect the pathogenesis of some types of tumor 15-20." (PMID 33976737, 2021). "Our research further clarifies that TREM2 has a broader range of tumor applicability and confirms that TREM2 expression is closely involved in the biological processes of immune cells and immune-related molecules across most cancers." (PMID 33679809, 2021). "Compared with other immune cells, the macrophages in the primary tumor (i.e., TAMs) exclusively exhibited high expression of the SAMs signature genes (Chil3, Trem2, C1qa, and C1qb), whereas Plac8 and Ly6c2 were broadly expressed across cell types." (PMID 33782087, 2021). "Here, we reviewed the recent advances in the study of TREM2, especially focused on its regulation of tumor-related immune signaling pathways and its role as a novel target in cancer immunotherapy." (PMID 34539652, 2021). "Our study also revealed that TREM2 expression was correlated with tumor stage in the majority of cancers, and was particularly different between stage I and II tumors." (PMID 33679809, 2021). "In summary, our first pan-cancer analyses of TREM2 indicates that this factor is differentially expressed between tumor and normal tissues and reveals correlations of TREM2 expression with clinical prognosis and DNA methylation." (PMID 33679809, 2021). "To investigate the biological significance of TREM2 expression in different tumor tissues, we conducted GESA and GSVA." (PMID 33679809, 2021). "TREM2 can alter the morphology of tumor-infiltrating macrophages, inhibit tumor growth, and enhance checkpoint blocking therapy." (PMID 33679809, 2021). "Next, we analyzed the expression of CXCL5, CXCL8, IL18RAP, and TREM2 in paired tumor and adjacent normal tissues." (PMID 33955820, 2021). "Using multiplexed immunohistochemistry, C1Q+TREM-2+ TAMs were found to be tumor-specific and C1Q+TREM-2+APOE+ TAMs located significantly nearer the tumor cells than triple-negative TAMs." (PMID 34831009, 2021). "We also explored the potential associations between TREM2 expression and microsatellite instability (MSI), tumor mutational burden (TMB), DNA methylation, and immune infiltration levels across 33 types of cancer." (PMID 33679809, 2021). "New subsets of tumor-promoting myeloid cells are constantly discovered, such as recently described TREM2(triggering receptor expressed on myeloid cells 2)-expressing cells." (PMID 33801964, 2021). "Owning to the complexity of HCC, there are still many issues regarding the function and mechanism of TREM1 and TREM2 that need to be further studied, including the role of the gene and the tumor microenvironment." (PMID 33297569, 2020). "TREM2 plays a protective role by suppressing inflammation, decreasing lipid-related gene expression, and suppressing tumor progression." (PMID 33297569, 2020). "Investigators went on to demonstrate that a subset of TREM2 expressing myeloid cells played a crucial role in the formation of an immunosuppressive tumor microenvironment." (PMID 33173037, 2020). "Knockdown of TREM-2 inhibited cell growth and induced cell cycle arrest and apoptosis of tumor cells." (PMID 32684831, 2020). "In a study using HepG2 cells and an HCC model animal, PI3K/AKT was the pathway induced by TREM2 to regulate the biological behavior of the tumor cells." (PMID 33297569, 2020). "It is also important to note that some reports identified TREM2 as tumor suppressor based on its expression in malignant cells." (PMID 33173037, 2020). "To clarify the anti-tumorigenic effect of TREM2 in vivo, we investigated tumor incidence in WT mice injected subcutaneously with MC38 cells transfected with vector or TREM2 plasmid and DAP12 cells." (PMID 31489935, 2019).